MMP1 (matrix metallopeptidase 1)
Diseases named in the same sentence as MMP1 in open-access papers (continued):
Sharing a sentence is not in itself a finding about the gene and the disease.
osteoarthritis (85 papers, 2005 to 2026). A noninflammatory degenerative joint disease occurring chiefly in older persons, characterized by degeneration of the articular cartilage, hypertrophy of bone at the margins and changes in the synovial membrane. "Expression of MMP‐1, which has a collagenase effect, has been associated with the pathogenesis of osteoarthritis, and high levels have been observed in cases of osteoarthritis." (PMID 40434930, 2025). "Alternatively, the altered biomechanics and microstructural kinematics observed after MMP-1 can alter force distribution at the joint’s articulation and cause downstream effects on cartilage health, a common progression in degenerative joint disease." (PMID 35992346, 2022). "The present study explored the effects of Eucommia on the levels of MMP-1, -3 and -13 in rats with osteoarthritis; however, the underlying mechanisms remain unclear." (PMID 24137247, 2013). "In addition to the established role of MMP-1 in COPD, elevated expression of MMP-1 has been associated with a variety of pathological conditions such as rheumatoid and osteoarthritis, atherosclerosis, Alzheimer disease, and cancer." (PMID 22992122, 2012). "In a mouse model of posttraumatic osteoarthritis, curcumin has been found to slow the progression of osteoarthritis and relieve its symptoms by reducing the levels of MMP-1, MMP-3, MMP-13, ADAMTS5, IL-1β, and TNF-α." (PMID 37938371, 2024). "An independent clinical trial of LC supplementation in patients with osteoarthritis showed that LC significantly reduced serum levels of IL-1b and MMP-1." (PMID 38674921, 2024). "Among various MMPs, MMP-1, MMP-3, and MMP-13 are reported to demonstrate increased expression in osteoarthritis and are closely associated with its development." (PMID 38542192, 2024). "In osteoarthritis (OA) synovial cells stimulated by visfatin and resistin, an increase in MMP-1 and MMP-13 expression, along with a decrease in Col2a1 expression, has been observed." (PMID 39409194, 2024). "In in vitro and in vivo models of osteoarthritis, shikonin inhibited inflammatory responses by reversing the elevated expression of MMP1, MMP3, and MMP13." (PMID 34812264, 2021). "Other contributions to osteoarthritis from activities related to MMP-3 include MMP-3-mediated activation of MMP-1 and MMP-13." (PMID 32116759, 2020). "Level of leptin in synovial fluid of osteoarthritis patients undergoing total knee replacement surgery positively correlated with the levels of MMP-1 and MMP-3." (PMID 33396484, 2020). "Isolated RA synovial fibroblasts have shown reduced expression of p21 relative to osteoarthritis (OA) synovial fibroblasts and adenovirus-mediated delivery of p21 suppresses the spontaneous production of IL-6 and MMP1 in RA synovial fibroblasts." (PMID 31160890, 2019). "The primary enzymes responsible for cartilage and bone degradation in osteoarthritis are MMPs, most predominantly MMP-1, -2, -3, -9, and -13." (PMID 31382623, 2019). "Serum cartilage oligomeric matrix proteins (COMP), bone alkaline phosphatase (bALP), osteocalcin, PINP, synovial fluid hyaluronic acid and MMP‐1 levels at 0 h, 15, 30 and 60 days in dogs with osteoarthritis treated with meloxicam and pentoxifylline (Mean ± SD)." (PMID 40434930, 2025). "In human osteoarthritis synovium, paquinimod treatment blocked MMP1 and MMP3 secretion." (PMID 33005006, 2020). "Given that MMP-1, MMP-3 and MMP-13 play pivotal roles in the cartilage matrix breakdown associated with both RA and osteoarthritis, the inhibitory effects of acacetin on MMPs indicates a potential role for acacetin in preventing cartilage degradation associated with RA." (PMID 25856795, 2015). "Our findings indicate that the use of the CO generation compound (CORM-II) or the induced expression of HO-1 down-regulates the ROS production by Nox4 in human C-20/A4 chondrocytes that consequently reduce MMP-1 secretion and cell death, two main features in osteoarthritis." (PMID 23840483, 2013).
osteoarthritis (continued). "In human osteoarthritis chondrocytes, ET-1 controls the production of MMP-1 and MMP-13." (PMID 15743480, 2005). "Furthermore, Matrix metallopeptidase 1 (MMP-1) is a major collagenase related to human joint diseases that has been applies as a diagnostic marker for human osteoarthritis, but MMP-1 is not expressed in rodents." (PMID 34837955, 2021). "Osteoarthritis (OA) is characterized by the accumulation of chondrocytes expressing p16INK4a and markers of the senescence-associated secretory phenotype (SASP), including the matrix remodeling metalloproteases MMP1/MMP13 and pro-inflammatory cytokines interleukin-8 (IL-8) and IL-6." (PMID 24572376, 2014). "Prior clinical investigations reported that patients with RA have elevated serum and synovial fluid levels of MMP-1 and MMP-3 compared to osteoarthritis patients and normal ones, correlated to the levels of other disease activity markers." (PMID 40350466, 2025). "In chondrocytes derived from osteoarthritis patients, GEN suppressed the IL1β-induced expression of NOS2, COX-2, MMP1, MMP2, MMP3, and MMP13." (PMID 37513300, 2023). "The same study revealed that oral administration of sesamol (30 mg/kg, p.o.)for 2 weeks attenuated MMP-1 and MMP-9 expression in the cartilage of monosodium iodoacetate (MIA)-induced osteoarthritis in male Wistar rats." (PMID 34760018, 2021). "TNF-α’s activity blockade through soluble PEGylated TNFR1 was shown to decrease the production of MMP-1, MMP-3 and MMP-13 in femoral condylar cartilage cells cultured from osteoarthritis patients." (PMID 34201546, 2021). "MMP-1 and MMP-3 likely participate in cartilage destruction in rheumatoid arthritis and osteoarthritis." (PMID 32116759, 2020). "Previous report has shown that increased MMP-1, MMP-3, MMP-9, MMP-12, and MMP-13, VEGF-A, and COL10A1, triggered by hypoxia-inducible factor (HIF)-2, play a vital role during osteoarthritis development." (PMID 31766662, 2019). "Compared with the control group, the mRNA and protein levels of MMP1, MMP3, and MMP13 increased significantly in IL-1β-stimulated human osteoarthritis chondrocytes." (PMID 29179489, 2017). "Specific MMPs, such as MMP-1 (collagenase-1), MMP-3 (stromelysin-1), and MMP-13 (collagenase-3), degrade cartilage proteoglycans and type II collagen, leading to osteoarthritis." (PMID 29348767, 2017). "The study set out to determine the levels of metalloproteinases MMP-1, MMP-3 and MMP-8, as well as tissue inhibitor TIMP-1 in patients with osteoarthritis, following the administration of anti-rheumatic agents." (PMID 32185271, 2017). "The present study investigated the effects of an aqueous extract of Eucommia on the articular cartilage (by Mankin’s grade) and the levels of matrix metalloproteinase-1 (MMP-1), MMP-3 and MMP-13 in the serum and synovial fluid in a rat model of osteoarthritis." (PMID 24137247, 2013). "TauCl also differentially inhibits the expression of MMP-1 and MMP-13, which play dominant roles in RA and osteoarthritis (OA), in IL-1β-stimulated fibroblast-like synoviocytes (FLS)." (PMID 20804602, 2010). "The levels of adiponectin, VEGF, MMP-1, and MMP-13 in the joint fluids from 30 RA or osteoarthritis (OA) patients were also measured." (PMID 19883500, 2009). "The mechanism of endothelin-1 (ET-1)-induced nitric oxide (NO) production, MMP-1 production and MMP-13 production was investigated in human osteoarthritis chondrocytes." (PMID 15743480, 2005). "Sleep deprivation could activate the p-ERK pathway in rat mandibular condylar chondrocytes, increases the expression of matrix-degrading enzymes MMP1, MMP3, and MMP13, and leads to osteoarthritis-like lesions in the temporomandibular joint." (PMID 39010104, 2024). "Human osteoarthritis chondrocytes can be inhibited by senegenin by inhibiting PI3K/AKT/NF-κB signaling pathway, inhibiting the expression of MMP-1, MMP-3, and MMP-13 induced by IL-1β, and the production of NO and PGE2 was reduced in human osteoarthritis chondrocytes." (PMID 35924058, 2022).
osteoarthritis (continued). "MMP-1 has been found to be overproduced in osteoarthritic rather than normal chondrocytes, demonstrating the important role of MMP-1 in the pathogenesis of osteoarthritis." (PMID 34765365, 2021). "For example, WISP-3 overexpression in normal cartilage (C-28/I2) cells dramatically reduces the expression of ADAMTS-4 and ADAMTS-5, and markedly elevates matrix metalloproteinase-1 (MMP-1) and MMP-10 expression, leading to the degradation of cartilage and the development of osteoarthritis." (PMID 34680447, 2021). "TQ (intra-articularly injection of 0.3 mL; 10 mmol/L) also upregulated the expression of MMP-1 (matrix metalloproteinase-1) (tissue inhibitors) and downregulated MMP-13 in both rabbit chondrocytes and animal models of osteoarthritis induced by anterior cruciate ligament transaction." (PMID 34067322, 2021). "Similarly, leptin alone and by co-stimulation with IL-1ß enhanced the production of MMP-1, MMP-3, and MMP-13 in knee cartilage from patients with osteoarthritis." (PMID 33396484, 2020). "The high expression of TIMP-1, MMP-1 and MMP-13 in the cartilage may be responsible for the degeneration, and PCL rupture may trigger meniscus degradation and ultimately osteoarthritis." (PMID 30626725, 2019). "Matrix metalloproteinase 1 (MMP-1) degrades cartilage, which may result in osteoarthritis (OA) development." (PMID 30177524, 2018). "MMP-1 and MMP-3 are the main MMPs produced by fibroblasts and macrophage-like cells in the synovium, with significantly higher levels found in the synovial fluid of patients with RA compared to patients with osteoarthritis." (PMID 27564851, 2016). "In particular, the MMP-1 and MMP-13 collagenases play dominant roles in RA and osteoarthritis." (PMID 20804602, 2010). "In addition, MMP1 and MMP13 collagenases play dominant roles in RA and osteoarthritis because they are the rate-limiting components of the collagen degradation process." (PMID 19327174, 2009). "Importantly, our study revealed that FA suppressed MMP‐1, MMP‐3, and MMP‐13 production stimulated by IL‐1β in vitro, suggesting that FA may be effective for restoring ECM composition and structure to halt osteoarthritis progression." (PMID 34078001, 2021). "In addition, studies have shown that LDW pills could effectively inhibit the expression of IL-beta, MMP-1 and MMP-3, thus protecting and repairing the articular cartilage which had significant therapeutic effects on Osteoarthritis." (PMID 29212201, 2017).
colorectal cancer (77 papers, 2004 to 2026). A primary or metastatic malignant neoplasm that affects the colon or rectum. "Our computational study confirmed that colorectal cancer had also been associated with the upregulation of 16 genes, such as MMP1, and the downregulation of one gene (ACAA1)." (PMID 38528462, 2024). "This study aimed to investigate the association between CTGF and MMP-1 mRNA expressions with clinicopathological status and survival rate in colorectal cancer patients." (PMID 35456495, 2022). "In colorectal cancer, MMP1 derived from tumor-associated macrophages activates MAPK/Erk signaling pathway through paracrine PAR1 activation, ultimately facilitating colon cancer cells proliferation." (PMID 35333672, 2022). "Accumulating evidence shows that aberrant expression of MMP-1 has been implicated in the progression of various human cancers, such as colorectal cancer, lung adenocarcinoma and ESCC." (PMID 34741018, 2021). "Elevated MMP-1 expression has been associated with several tumours such as peritoneal metastasis in gastric cancer, colorectal cancer, and cutaneous melanoma cancer." (PMID 30423799, 2018). "Overexpression of MMP-1 protein is associated with poor prognosis of esophageal cancer and colorectal cancer." (PMID 24505369, 2014). "Increased expression of MMP-1 has been associated with a poor prognosis in several malignancies such as colorectal carcinoma, bladder carcinoma, oral carcinoma and nasopharyngeal carcinoma." (PMID 20152059, 2010). "As considerable evidence has implicated the upregulation of MMP-1, -2, -3, -7, -9, and -13 in the development of human colorectal cancers, further studies are needed to investigate the effects of PLE0 on various MMP activities using ITC or thermal shift assays." (PMID 38732748, 2024). "Similarly, an aberrant expression of MMP-1 has been shown to be associated with poor prognosis in colorectal cancer." (PMID 36765641, 2023). "MMP-1 expression is associated with poor prognosis in colorectal cancer." (PMID 33833342, 2021). "The decreased expression of NT3 was also observed in colorectal cancer, while increased levels of plasma MMP1 have been associated with coronary atherosclerosis and cancers providing further evidence to support the role of these proteins in disease development during aging." (PMID 31507593, 2019). "In addition, overexpression of MMP1 protein is associated with poor prognosis of esophageal cancer and colorectal cancer." (PMID 28612708, 2017). "Only MMP-1 (-1607 1G/2G) polymorphism was associated with colorectal cancer." (PMID 20152059, 2010). "Being a member of MMP family, MMP-1 has been reported to play an important role in cancer invasion through overexpression, which is associated with metastasis and poor prognosis in esophageal cancer, ovarian cancer, cutaneous malignant melanoma, colorectal cancer and gastric cancer." (PMID 24505369, 2014). "ADAMDEC1+ fibroblasts and MMP1+ CAFs were more abundant in primary colorectal cancer (mCC and nCC) than in metastatic liver cancer (mLC)." (PMID 41031085, 2025). "Similar findings have been reported for MMP1 in colorectal cancer (CRC), where knockdown experiments confirmed its protumorigenic role." (PMID 39596132, 2024). "In line with this, we interpret the reductions in the protein levels of MMP-1, -2, and -3 following all the pomace treatments as having potential positive implications in colorectal cancer." (PMID 39200479, 2024). "For instance, darifenacin blocks the muscarinic acetylcholine receptor 3 in colorectal cancer cells, leading to a decrease in the p38, Erk and Akt signaling pathways, as well as the disruption of MMP-1 mRNA expression." (PMID 39225813, 2024). "It was confirmed that colorectal cancer tissues (cancer cells and stroma cells) show elevated immunoreactivity of MMP-1, and the intensity of its expression is correlated with the depth of cancer invasion into intestinal structures." (PMID 39337393, 2024).
colorectal cancer (continued). "Involvement of the AhR-regulated MMP-1/EGFR signaling in colorectal cancer pathogenesis was indicated as the suppression of MMP-1, a gene induced by AhR, led to the improvement of colorectal cancer by inhibiting EGFR-downstream PI3K/AKT signaling." (PMID 39211042, 2024). "MMP1 promotes colorectal cancer 41 and esophageal squamous cell carcinoma 42 proliferation by activating PI3K-AKT signaling pathway." (PMID 35414794, 2022). "Vice versa, knocking down CAMSAP2 by lentivirual shRNAs reduced the mRNA levels of MMP-1 in both tested colorectal cancer cells." (PMID 36207462, 2022). "Elevated expression of MMP1 and its prognostic value have been revealed in colorectal cancer, cervical squamous cell carcinoma, uveal melanoma, and colon cancer." (PMID 36105241, 2022). "Taken together, these data demonstrated that CAMSAP2 transcriptionally upregulated MMP-1 in colorectal cancer cells." (PMID 36207462, 2022). "For instance, knockdown of MMP1 inhibited the progression of colorectal cancer by suppressing the PI3K-Akt-myc signaling pathway and EMT." (PMID 36105241, 2022). "For example, MMP1 was highly expressed in colorectal cancer tissues and its high expression was related to lymphatic metastasis and TNM stage." (PMID 35426219, 2022). "By gain- and loss-of function experiments, we demonstrated that MMP-1 was a substantial downstream target of CAMSAP2, and it played a crucial role in regulating the migration and invasion induced by CAMSAP2 in colorectal cancer cells." (PMID 36207462, 2022). "Complementally, downregulation of MMP1 inhibits the progression of colorectal cancer by suppressing the PI3K/Akt/c-myc signaling pathway and epithelial-mesenchymal transformation (EMT)." (PMID 36105241, 2022). "ascertained the MMP1-dependent effect in hepatocellular carcinoma (HCC) progression via interacting with HuR and the metastasis of colorectal cancer via orchestrating the DDX3/YY1/MMP1/PI3K-AKT axis, respectively." (PMID 36483054, 2022). "Another study showed that MMP1 was involved in the cancer-promoting effect of TCONS_00012883 on colorectal cancer." (PMID 36727076, 2022). "On the contrary, inhibition of MMP-1 by chemical inhibitors or neutralizing antibodies drastically reduced the abilities of migration and invasion in colorectal cancer cells." (PMID 36207462, 2022). "Among the candidate genes, MMP1 positively correlated with SERPINE1 in the TCGA colorectal cancer cohort (R = 0.51)." (PMID 36076991, 2022). "The latest investigations indicate that MMP1 plays a vital role in EMT in colorectal cancer and squamous cell carcinoma of the skin." (PMID 36105241, 2022). "In colorectal cancer, MMP1 overexpression was positively correlated with TNM stage and lymphatic metastasis." (PMID 36105241, 2022). "NR3C2, CA2, and MMP1 were identified as key target proteins in another network pharmacological pharmacology analysis of the colorectal cancer." (PMID 34381520, 2021). "The knockdown of MMP1 inhibits the progression of colorectal cancer by suppressing the PI3K/Akt/c-myc signalling pathway and epithelial–mesenchymal transition." (PMID 34445346, 2021). "Ginsenoside Rh1 (Rh1) inhibited colorectal cancer cell migration and invasion by partial inhibition of MMP1 and MMP3." (PMID 33921173, 2021). "In different study populations higher circulating levels of MMP-1, MMP-2 and MMP-3 were strongly associated with all-cause mortality in patients with colorectal cancer, myocardial infarction or heart failure." (PMID 28446168, 2017). "The upregulation of MMP1 mRNA has been found in the tissues from the patients of various types of cancer, such as colorectal cancer, esophageal cancer and GC." (PMID 28612708, 2017). "Description of upregulation of several MMPs - among them MMP1,2,3,7,9,10,11,12,13 - in cancerous tissue of colorectal cancer patients is common." (PMID 27431388, 2016).